HIPK2 (homeodomain interacting protein kinase 2)
Diseases named in the same sentence as HIPK2 in open-access papers (continued):
Sharing a sentence is not in itself a finding about the gene and the disease.
breast carcinoma (15 papers, 2010 to 2025). "The use of the DEMETER2 computation method to screen for cancers that are specifically vulnerable to loss of HIPK2 revealed breast cancer as the top cancer identities." (PMID 32984337, 2020). "Our data suggest that TP63, YWHAZ, BRCA1, CCND2, YWHAG, and HIPK2 can be potential genetic markers of prognostic assessment, immune infiltration and chemotherapeutic drug sensitivity in breast cancer patients." (PMID 36673982, 2023). "In MCF7 breast cancer cells, HIPK2 knockdown is correlated with metallothionein 2A (MT2A) up regulation." (PMID 26493598, 2015). "In contrast, in breast cancer cells, HIPK2 is degraded during periods of low oxygen via association with the E3 ubiquitin ligase SIAH2; this degradation of HIPK2 is necessary as the protein normally represses the expression of HIF-1α by binding at its promoter." (PMID 35285794, 2022). "HIPK2 is one of the most inter-connected targets of Module-2 miRs and it is considered to be an onco-suppressor, as it is a pro-apoptotic agent and it inhibits the invasiveness of breast cancer cells." (PMID 25961594, 2015). "In addition, HIPK2 has been shown to inhibit the growth and invasiveness of breast cancer cells." (PMID 25961594, 2015). "In this regard, it has been shown that HIPK2 negatively regulates MT2A gene, whose mRNA transcript isoform appears to be associated with cell proliferation in invasive ductal cancer tissues and that, on the contrary, HIPK2 depletion correlates with MT2A up-regulation in MCF7 breast cancer cells." (PMID 20876941, 2010). "In breast cancer cells, SIAH2 partially controls the overall hypoxia response through its effects on the stability of HIF1α, as by ubiquitylation and degradation of homeodomain-interacting protein kinase 2 (HIPK2)." (PMID 37268944, 2023). "Our analysis revealed that the five unique hub genes (PPARG, HIPK2, ZFP36L1, HMGB2 and ALDH1A3) may constitute a gene expression signature specifying a therapeutic response of ERβ1-expressing ERα-positive breast cancer cells to treatment with OHT+ATRA." (PMID 36835157, 2023). "In support to this notion, a direct function of HIPK2 for breast cancer cell migration was described and it will be interesting to find a role of HIPK2 and further members of the HIPK family for hormone-dependent breast cancers in future studies." (PMID 32984337, 2020).
renal fibrosis (15 papers, 2015 to 2025). A final common manifestation of a wide variety of chronic kidney diseases characterized by glomerulosclerosis and tubulointerstitial fibrosis. "The effect of HIPK2 loss in RTECs was first tested with a unilateral ureteral obstruction (UUO) model of renal fibrosis." (PMID 32701510, 2020). "HIPK2 expression was elevated in various human kidney diseases and associated with renal fibrosis progression." (PMID 32701510, 2020). "In all three separate models of CKD, loss of HIPK2 resulted in attenuation of renal fibrosis, consistent with the role of HIPK2 as a regulator of gene expressions involved in tubular injury and fibrosis." (PMID 25972814, 2015). "Additionally, HIPK2 has been implicated in renal fibrosis in recent studies." (PMID 36553510, 2022). "In CKD, its expression is increased in kidney epithelial cells, and knocking out HIPK2 in mice (global or tubular cell specific) effectively reduces renal fibrosis and improves kidney function." (PMID 38512421, 2024). "HIPK2 exhibits elevated expression in renal models of renal fibrosis and patients with chronic kidney diseases, concurrently modulating fibrosis and inflammatory processes." (PMID 39598332, 2024). "Background/Objectives: Homeodomain-interacting protein kinase 2 (HIPK2) is critically involved in the progression of renal fibrosis." (PMID 39598332, 2024). "Among several compounds containing benzimidazole and pyrimidine scaffolds, compound 15q was found to have a potent inhibitory activity against HIPK2 and, as a proof of principle, it was tested on renal cells and on mouse models of renal fibrosis." (PMID 36831402, 2023). "The role of HIPK2 in renal fibrosis has been confirmed in mice with unilateral ureteral obstruction and mice with acute kidney injury." (PMID 36553510, 2022). "Experimental and bioinformatics studies have identified HIPK2 as a key regulator of renal fibrosis, and both immunodeficient Tg26 mice and patients with various kidney diseases showed upregulated HIPK2 levels in the kidneys." (PMID 36553510, 2022). "Taken together, our findings suggest that SIRT6/HIPK2 axis is a potential target to intervene renal fibrosis and delay CKD progression." (PMID 36172184, 2022). "Recently, HIPK2 is regarded as a central contributor to renal fibrosis and accounts for multiple pro-fibrosis signaling pathways including TGF-β, Wnt/β-catenin and Notch pathway." (PMID 36172184, 2022). "Modulation of HIPK2 expression in murine renal tubular epithelial cells reveals an important role in renal fibrosis development." (PMID 32701510, 2020). "Here, we show that modulation of tubular HIPK2 expression and activity affects renal fibrosis development in vivo." (PMID 32701510, 2020). "It is reported that miR-141, a member of the miR-200 family, can inhibit EMT, and regulate renal fibrosis via TGF-β1/miR-141/HIPK2/EMT axis." (PMID 31906852, 2020). "We previously used global Hipk2-null mice in various models of kidney disease to demonstrate the central role of homeodomain-interacting protein kinase 2 (HIPK2) in renal fibrosis development." (PMID 32701510, 2020). "In summary, these data collectively suggest inhibitors of HIPK2, either inhibiting the kinase activity or its interaction with downstream effectors such as Smad3, would be therapeutically effective against renal fibrosis in CKD." (PMID 32701510, 2020). "Together, these results establish an important RTEC-specific role of HIPK2 in kidney fibrosis and further substantiate the inhibition of HIPK2 as a therapeutic approach against renal fibrosis." (PMID 32701510, 2020).
renal fibrosis (continued). "Here, we provide strong evidence to support the critical role of HIPK2 in RTECs in the progression of kidney fibrosis in 3 experimental models of renal fibrosis (UUO, Tg26, and FAN)." (PMID 32701510, 2020). "The effect of kinase-dead HIPK2 overexpression in RTECs was then examined in UUO-induced renal fibrosis." (PMID 32701510, 2020). "Conversely, WT HIPK2 overexpression in RTECs accentuated the extent of renal fibrosis in the setting of UUO, HIVAN, and folic acid–induced nephropathy in mice." (PMID 32701510, 2020). "No additive effects were observed in Pax8-HIPK2KD mice treated with BT173, indicating that both kinase activity of HIPK2 and interaction of HIPK2 with Smad3 are both required for HIPK2 to promote renal fibrosis." (PMID 32701510, 2020). "Our results indicate that the RTEC function of HIPK2 is a key mediator of renal fibrosis, and that increased HIPK2 expression and kinase activity are required for kidney fibrosis progression." (PMID 32701510, 2020). "Our conclusions are in agreement with some studies reporting that human HIPK2 promotes EMT in renal fibrosis." (PMID 29208636, 2018). "Other options to target renal fibrosis have recently included targeting homeodomain-interacting protein kinase 2 (HIPK2) or SMAD7 gene transfer." (PMID 28956186, 2017). "However, the high expression and crucial role of HIPK2 in renal fibrosis have been highly validated in various murine models and patients with chronic kidney diseases (CKDs)." (PMID 39598332, 2024). "As is widely known, HIPK2 is regarded as a crucial regulator of renal fibrosis." (PMID 39598332, 2024). "We previously demonstrated that homeodomain interacting protein kinase-2 (HIPK2), a signaling effector and transcriptional regulator with pleiotropic biological functions, is a key instigator of tubular cell injury, inflammation, and renal fibrosis in vivo." (PMID 38512421, 2024). "Given that HIPK2-CT expression reduced renal fibrosis in obstructed kidneys after 14 days after UUO, it may be plausible to target the overactive p65 activation in the setting of chronic renal inflammation by leveraging the actions of HIPK2-CT." (PMID 38512421, 2024). "Tubular cell–specific overexpression of HIPK2-CT attenuates renal fibrosis in obstructed kidneys." (PMID 38512421, 2024). "Recently, HIPK2 has been identified as a key regulator of inflammation and renal fibrosis." (PMID 36831402, 2023). "Recently, other molecules have been synthesized as HIPK2 inhibitors in renal fibrosis." (PMID 36831402, 2023). "Inhibiting of HIPK2 also exhibits a remarkable alleviation in renal fibrosis." (PMID 36172184, 2022). "ASH2L could activate the transcription of HIPK2 (a key regulator of renal fibrosis) and increase its protein expression through H3K4me3 in the HIPK2 promoter region, thereby mediating renal fibrosis and inflammation in DN." (PMID 36553510, 2022). "HIPK2 kinase activity and HIPK2-Smad3 interaction are both required for renal fibrosis progression." (PMID 32701510, 2020). "Considering that RTEC-specific loss of HIPK2 attenuated the renal fibrosis, we next explored whether RTEC-specific overexpression of HIPK2 could conversely augment renal fibrosis." (PMID 32701510, 2020). "RTEC-specific KO of HIPK2 mitigates renal fibrosis development." (PMID 32701510, 2020). "RTEC-specific overexpression of HIPK2 aggravates renal fibrosis in UUO and Tg26 mice." (PMID 32701510, 2020). "RTEC-specific overexpression of kinase-dead HIPK2 attenuates renal fibrosis." (PMID 32701510, 2020).
renal fibrosis (continued). "We next explored whether the kinase activity of HIPK2 was required for its effect on promoting renal fibrosis in vivo by generating a transgenic mouse model with RTEC-specific HIPK2 kinase-dead mutant overexpression." (PMID 32701510, 2020). "A published systematic approach identified HIPK2 as a key regulator of renal fibrosis." (PMID 25421593, 2015). "Notably, loss of HIPK2 reduced cellular responses to TGF-β during neuronal development and in mouse models of renal fibrosis." (PMID 25421593, 2015). "Therefore, inhibition of HIPK2 in these renal fibrosis models may be an effective therapeutic strategy." (PMID 39598332, 2024). "Together, these findings show an essential function of HIPK2 kinase activity in promoting renal fibrosis and suggest that overexpression of HIPK2 kinase-dead mutant protein attenuates renal fibrosis by acting as a dominant-negative against the endogenous HIPK2 in RTECs." (PMID 32701510, 2020). "The genetic or pharmacologic inhibition of HIPK2 attenuates the VAN-induced progression of AKI to CKD and prevents renal fibrosis, as evidenced by improved renal function, reduced tubular damage, and attenuated cell apoptosis." (PMID 36831402, 2023). "It has been shown that HIPK2 mediates NOX4 expression in diabetic kidneys and that phosphate niclosamide mitigates renal fibrosis by inhibiting HIPK2 expression in the tubulointerstitial compartment." (PMID 32701510, 2020). "We previously showed that the allosteric inhibition of HIPK2 and Smad3 interaction by small-molecule inhibitor BT173 effectively reduces the renal fibrosis in UUO and Tg26 mouse models." (PMID 32701510, 2020). "Since our initial publication, several recent studies further support the role of HIPK2 in RTEC injury and renal fibrosis." (PMID 32701510, 2020). "It has been reported that HIPK2 could promote the EMT process of renal tubular epithelial cells and renal fibrosis by activating the Smad pathway, Notch pathway, NF‐kB pathway and Wnt/β‐catenin pathway." (PMID 38186203, 2024). "For example, HIPK2 could promote the epithelial‐mesenchymal transition (EMT) process of renal tubular epithelial cells and renal fibrosis through activating the Smad pathway, Notch pathway, NF‐kB pathway and Wnt/β‐catenin pathway." (PMID 38186203, 2024). "As HIPK2 has been identified as a key regulator of renal fibrosis, we determined whether ASH2L affects HIPK2 expression." (PMID 36553510, 2022). "Although HIPK2 overexpression in RTECs had no observable effect in the sham-operated mice, it markedly augmented the renal fibrosis development after UUO." (PMID 32701510, 2020). "Moreover, whether caspase-6–mediated HIPK2 processing has any role in kidney cell injury or renal fibrosis has not been previously explored." (PMID 38512421, 2024).
colorectal cancer (12 papers, 2014 to 2024). A primary or metastatic malignant neoplasm that affects the colon or rectum. "The dysregulation of HIPK2 leads to diabetes, myocardial infarction, and colitis-associated diseases, including colorectal carcinoma and sepsis." (PMID 36362432, 2022). "The existence of an alternative splice variant of HIPK2, the HIPK2-∆e8 isoform, has been described in colorectal cancer." (PMID 32093146, 2020). "In the process of studying HIPK2 in human colorectal cancers, we identified a mutation (T566P) in a site we previously found autophosphorylated in mouse Hipk2." (PMID 28060750, 2017). "A similar consideration can be made on HIPK2, whose silencing in already transformed cancer cells has been consistently associated to resistance to chemotherapy, while its increased expression in stage II colorectal cancers has been shown to predict favorable response to adjuvant chemotherapy." (PMID 39342278, 2024). "As a proof of principle, inhibition of NRF2 has been shown to selectively induce cell death in NRF2-addicted colorectal cancer cells by promoting ferroptosis and pyroptosis and to increase chemotherapy response only when HIPK2 is expressed." (PMID 39062921, 2024). "We have previously shown that Homeodomain-Interacting Protein Kinase 2 (HIPK2) cooperates with KRAS in sustaining ERK1/2 phosphorylation in human colorectal cancers." (PMID 39342278, 2024). "Recently, HIPK2 has been shown to cooperate with KRAS signaling and associate with human colorectal cancer progression." (PMID 39342278, 2024). "With this purpose, we recently reported that at molecular level HIPK2 physically participates to RAS/MAPK complex, cooperates with KRAS signaling, and associates with tumor progression in human colorectal cancers." (PMID 39342278, 2024). "From this observation, we sought to take advantage and assessed the therapeutic potential of generating Hipk2 isoform unbalance in tumor-initiating cells derived from colorectal cancer patients." (PMID 26625198, 2016). "In 20 cases of normal colorectal cancer tissues, eight had low HIPK2 protein expression (−and +) and 12had high expression (++ and +++)." (PMID 25282590, 2014). "Thus, similarly to what was previously observed in human colorectal cancers, these data show that HIPK2 expression is maintained during pancreatic tumorigenesis." (PMID 39342278, 2024). "In summary, this study is the first to analyze the role of molecular cooperation of HIPK2 with KRAS signaling, already associated to colorectal cancer, in the KRAS-driven tumorigenesis of the pancreas using mice with tissue-specific expression of oncogenic KRAS and Hipk2-KO." (PMID 39342278, 2024). "In distinct colorectal cancer cells, SRSF3 silencing was demonstrated to enhance the selection of alternative 3′ splice site within the HIPK2 exon 8, generating the 81 nucleotides-deleted HIPK2 Δe8 isoform." (PMID 27983653, 2016).
lung carcinoma (10 papers, 2009 to 2023). "Recently, a genetic variant of HIPK2 has been found to be significantly related to radiation pneumonitis in lung cancer patients treated with radiation therapy, underscoring the role for HIPK2 in tissue inflammation and fibrosis after irradiation." (PMID 36831402, 2023). "Patients with the CC genotype of HIPK2: rs2030712 had a significantly increased risk of RP after radiotherapy for lung cancer." (PMID 31915028, 2020). "To verify HIPK2 amplification, we analyzed 6 lung cancer cell lines (A549, H460, H522, H1299, H2170, SKLU1) and normal LP9 cells using fluorescent in situ hybridization (FISH)." (PMID 33613845, 2021). "Inhibition of HIPK2 has been shown to protect lung cancer cells against UV-induced apoptosis while overexpression of HIPK2 sensitizes cells to UV-induced apoptosis and decreases cell proliferation." (PMID 21586138, 2011). "The HIPK2 siRNA (siExon2) decreased YAP protein stability in H2170 lung cancer cells." (PMID 33613845, 2021). "In conclusion, exosomal miR-1260b can promote angiogenesis in HUVECs and metastasis of NSCLC by regulating HIPK2 and may serve as a prognostic marker for lung cancers." (PMID 34321461, 2021). "In addition, homeodomain-interacting protein kinase 2 (HIPK2) is a member of the serine/threonine kinase family, and there is a clearly increased risk of RP in lung cancer patients with the CC genotype of HIPK2: rs2030712 after radiotherapy." (PMID 34572367, 2021). "We detected gain of HIPK2 copy number in lung cancer cell lines compared to the normal LP9 cells." (PMID 33613845, 2021).